AK4P3 (adenylate kinase 4 pseudogene 3)
Synonyms: AK3L2P; formerly AK3L2
Gene: Protein-coding gene on chromosome 12 (31,615,023 to 31,652,095, reverse strand). Ensembl gene ENSG00000233381.
Gene Ontology:
Molecular function: nucleoside diphosphate kinase activity; AMP kinase activity; ATP binding; nucleobase-containing compound kinase activity; nucleoside monophosphate kinase activity; nucleoside triphosphate adenylate kinase activity; phosphotransferase activity, phosphate group as acceptor
Biological process: AMP metabolic process; nucleoside triphosphate biosynthetic process; ADP biosynthetic process; ATP metabolic process; GTP metabolic process; nucleobase-containing small molecule metabolic process
Cellular component: mitochondrial matrix; mitochondrion
Genetic constraint (gnomAD): Missense variants: 33 observed, 68.27 expected, observed/expected ratio (o/e) 0.48, 90% interval 0.37 to 0.65. Synonymous variants: 13 observed, 26.94 expected, observed/expected ratio (o/e) 0.48, 90% interval 0.31 to 0.77.
Homologues: Orthologues: chimpanzee AK4 (99% identical), macaque AK4 (98% identical), dog AK4 (95% identical), rabbit AK4 (92% identical), mouse Ak4 (91% identical), rat Ak4 (90% identical), guinea pig AK4 (79% identical), tropical clawed frog ak4 (77% identical), zebrafish ak4 (63% identical), Caenorhabditis elegans F13E6.2 (25% identical), Drosophila melanogaster CG9541 (22% identical). Paralogues in human: AK4 (99% identical), AK3 (59% identical), AK2 (41% identical), AK5 (26% identical), AK7 (26% identical), AK8 (26% identical), AK1 (26% identical), CMPK1 (25% identical), AK9 (22% identical).